SIRT6 (sirtuin 6)
Diseases named in the same sentence as SIRT6 in open-access papers (continued):
Sharing a sentence is not in itself a finding about the gene and the disease.
liver cancer (21 papers, 2012 to 2025). An epithelial or non-epithelial malignant neoplasm that arises from the liver. "The risk score calculated by the expression value of HDAC1, HDAC2, HDAC4, HDAC11, HAT1, and SIRT6 was an independent risk factor for liver cancer." (PMID 36124029, 2022). "In contrast, loss of SIRT6 is a factor associated with shorter survival of breast and liver cancer patients in other reports." (PMID 33198792, 2020). "SIRT6 has been implicated in liver cancer either favorably or unfavorably." (PMID 36831330, 2023). "The capacity of SIRT6 to inhibit tumor formation consists in maintaining genome integrity, and downregulation of SIRT6 in ovarian, breast, colon, and liver cancers has been documented." (PMID 40149343, 2025). "In summary, this study provides a potential mechanism for the ablation of Sirt6, which triggers an increase in Serpina12 upregulation to induce a “lipid-rich” environment that favors liver cancer development." (PMID 38332150, 2024). "Studying Sirt6 whole body knockout mice, we have previously shown that a small fraction of the mutant mice developed lesions and liver cancer triggered by inflammation." (PMID 38332150, 2024). "The role of SIRT6 in liver cancer is quite complicated, as both tumor-suppressive and tumor-promoting activities have been documented in the literature." (PMID 36831330, 2023). "Another study suggests that SIRT6 plays a key tumor suppression function during the liver cancer initiation." (PMID 36831330, 2023). "SIRT6 is downregulated in human liver cancer, and SIRT6 knockout in HCC induces oncogenic changes including global hypomethylation, decreased apoptosis, and metabolic changes, such as increased fat deposition and hypoglycemia." (PMID 38203666, 2023). "As the role of SIRT6 in liver cancer remains incompletely understood, further characterization of the SIRT6 function in liver cancer development is needed." (PMID 36831330, 2023). "The c-Jun/c-Fos/SIRT6 pathway controls the liver cancer initiation and survival of initiated cancer cells." (PMID 38203666, 2023). "The suppression of SIRT6 in various liver cancer cell lines can inhibit cell growth and induce apoptosis in vitro." (PMID 35463332, 2022). "Downregulation of SIRT6 expression has been detected in liver cancer, whereas SIRT6 is found to be overexpressed in chronic lymphocytic leukemia (CLL) in patients with liver cancer and CLL, respectively." (PMID 33920726, 2021). "Overexpression of SIRT6 inhibited the proliferation of HepG2 liver cancer cells by suppressing the ERK1/2 pathway." (PMID 33198792, 2020). "For example, SIRT6 is downregulated in DOX-treated liver cancer cells, contributing to DOX-induced cell death." (PMID 32392755, 2020). "SIRT6 suppressed the initiation of liver cancer by inhibiting survivin expression in a liver cancer mouse model." (PMID 27824900, 2016). "In order to investigate the role of SIRT6 in liver cancer, the protein levels of SIRT6 were compared among an immortalized hepatocyte cell line, THLE-2, and such six HCC cell lines as Hep3B, HepG2, SNU475, SK-Hep1, SNU449 and Huh-7." (PMID 27824900, 2016). "The role of Sirtuin 6 (SIRT6) as a tumor suppressor or oncogene in liver cancer remains controversial." (PMID 27824900, 2016). "In an analysis of the Oncomine Cancer Microarray database containing 153 primary human liver cancers and cirrhotic and normal livers, SIRT6 mRNA levels were found to be significantly lower in the liver cancers and cirrhotic livers than they were in the normal livers." (PMID 36831330, 2023). "The level of SIRT6 decreases with increasing liver cancer grade, and increasing the level of SIRT6 at the initiation stage could significantly impair the development of cancer." (PMID 35463332, 2022). "SIRT6 suppression is regulated via the c-Fos pathway in hepatic cancer." (PMID 33920726, 2021). "SIRT6 levels were higher in liver cancer cells than THLE-2 cells." (PMID 27824900, 2016).
liver cancer (continued). "The reported functions of SIRT6 in liver cancer have also been inconsistent." (PMID 27824900, 2016). "A number of reports also suggest that SIRT6 may also be involved in the promotion of liver cancer." (PMID 36831330, 2023). "However, some studies have found that SIRT6 inhibits the development of liver cancer." (PMID 35463332, 2022). "Importantly, SIRT6 depletion may inhibit MDR1 expression at transcriptional level to increase the sensitivity of the liver cancer cells to chemotherapeutic agents." (PMID 29563873, 2018). "In human liver cancer, the expression of USP48 is downregulated, reducing the stability of SIRT6, which induces the occurrence of liver cancer." (PMID 36578520, 2022). "In liver cancer, multiple different groups’ investigations showed that METTL14 inhibits EMT, invasion and metastasis of liver cancer cells by regulating m6A-modified target mRNAs such as EGFR/PI3K/AKT, DGCR8/primiR-126, USP48/SIRT6/glycolysis, CSAD, GOT2 and SOCS2." (PMID 40734692, 2025). "Our examination of Sirt6-LKO mice at about two years of age clearly detected spontaneous HCC formation in 6 out of 7 (86%) mutant mice, which is more than triple as much as the control (B and EV5A), suggesting that Sirt6 is a tumor suppressor in liver cancer." (PMID 38332150, 2024). "Similarly, our findings showed that Sirt6-LKO also results in a mixed tumor pattern, which is accelerated in a DEN-induced liver cancer model." (PMID 38332150, 2024). "Previous study reported that SIRT6 promoted cell death during liver cancer initiation in diethylnitrosamine (DEN)-induced mouse liver cancer model, which suggests that SIRT6 might be a tumor suppressor in HCC tumorigenesis." (PMID 29100306, 2017). "SIRT6 protein is decreased in human dysplastic liver nodules but not in malignant liver tumors." (PMID 36831330, 2023). "Furthermore, since Sirt6-LKO mice were studied for no longer than 13 months and no tumors were observed in this stage, the contribution of Sirt6 to liver cancer development remains unknown." (PMID 38332150, 2024).
Hypertension (20 papers, 2011 to 2025). The presence of chronic increased pressure in the systemic arterial system. "The aim of the study was to explore the role of SIRT6 in the development of hypertension and the molecular mechanisms involved." (PMID 40218970, 2025). "Recent research has indicated that SIRT6, through epigenetic modulation, can prevent hypertension-induced endothelial dysfunction." (PMID 38992162, 2024). "In supporting of this, literature argued that endothelial Sirt6 plays a regulatory role in preventing hypertension by aiming at GATA5 (GATA binding protein 5) signaling pathway." (PMID 37497437, 2023). "Although many experiments exploring Sirt6 function in secondary hypertension have been conducted, the exact etiology of primary hypertension remains reclusive, to the best of our knowledge." (PMID 37497437, 2023). "Endothelial overexpression of SIRT6 showed therapeutic potential in deoxycorticosterone acetate/salt-induced hypertension and related cardiorenal syndromes in mice." (PMID 35855341, 2022). "This study explored the role of Sirt6 in the pathogenesis of hypertension and focused on the role of mitochondrial fission in podocyte injury." (PMID 35842903, 2022). "In contrast, SIRT6 treatment prevented Ang II-mediated hypertension, pathological hypertrophy, myocardial fibrosis, dysfunction and injury by upregulation of ACE2 levels and suppression of the FKN signaling." (PMID 29069788, 2017). "Additionally, SIRT6 maintains endothelial function and prevents hypertension through Nkx3.2-GATA5 signaling." (PMID 41567643, 2025). "SIRT6 keeps the endothelium function intact, preventing hypertension and its consequences." (PMID 41567643, 2025). "Sirt6 also exerts a modulatory effect on kidney diseases including obstructive nephropathy and chronic kidney disease, contributing to the subsequent outcome of kidney disease-induced hypertension, also known as secondary hypertension." (PMID 37497437, 2023). "Pathologically, hypertension is characterized by arterial calcification, and one paper reported that capsaicin alleviates arterial calcification by upregulating Sirt6-mediated deacetylation of HIF1α, highlighting a potential therapeutic method for treating arterial calcification, even hypertension." (PMID 37497437, 2023). "The critical functions of SIRT6 in regulating ECs and VSMCs also affect hypertension." (PMID 35855341, 2022). "In hypertension and related nephropathy, SIRT6 may also inhibit ACE2 expression in ECs, which requires further in vivo validation." (PMID 35855341, 2022). "In addition, Sirt6 prevented the complications of pathological hypertension by maintaining endothelial function through the epigenetic regulation of Nkx3.2‐mediated GATA5 signalling." (PMID 35842903, 2022). "Thus, SIRT6 may also repress hypertension and PAH by maintaining VSMCs and ECs “young”." (PMID 35855341, 2022). "SIRT6, a member of the NAD+-dependent deacetylase (Class III HDAC), ultimately prevented hypertension and its complications, making SIRT6 a new therapeutic target for hypertension." (PMID 39125279, 2024). "Although SIRT6 has been shown to improve the expression of intercellular TJ proteins in hypertension and colitis 19, 32, its role in LPS-induced ARDS has not been elucidated." (PMID 37082736, 2023). "The purpose of this study was to examine age-related expression patterns of these signaling molecules, in particular MT, SIRT1, SIRT3, and SIRT6 in BE of subjects of different ages with and without arterial hypertension (AH)." (PMID 33143333, 2020). "Podocyte or endothelial cell-specific Sirt6 knockout mice have been used to illustrate the detrimental effects of the regulation of histone H3K9 acetylation on diabetic nephropathy or adriamycin-induced podocyte injury and angiotensin II-induced hypertension and its complications." (PMID 35563783, 2022).
Hypertension (continued). "Previous studies demonstrated that SIRT6 expression is downregulated in human failing hearts and mice hearts subjected to transverse aortic constriction (TAC) or chronic infusion of hypertrophic agonists isoproterenol or Ang II, which may play a pivotal role in the etiology of hypertension." (PMID 29069788, 2017).
osteoarthritis (20 papers, 2015 to 2026). A noninflammatory degenerative joint disease occurring chiefly in older persons, characterized by degeneration of the articular cartilage, hypertrophy of bone at the margins and changes in the synovial membrane. "Prior studies noted that chondrocyte SIRT6 activity is repressed in older chondrocytes rendering cells susceptible to catabolic signalling events implicated in osteoarthritis (OA)." (PMID 37550003, 2023). "Sirt6 has been implicated as a key regulator in aging-related diseases, including osteoarthritis." (PMID 36496445, 2022). "Recently SIRT6 deficiency was found to be involved in several bone metabolism disease, such as osteoporosis and osteoarthritis, which may due to the broken balance of bone homeostasis." (PMID 34239868, 2021). "In recent years, studies have shown that some natural compounds and small molecule compounds can act as specific activators of SIRT6 and thus have potential therapeutic value for osteoarthritis." (PMID 41154537, 2025). "The literatures indicated that mir-486 promoted transition of catabolic phenotype in chondrocyte-like cells by directly targeting Sirt6 in patients with severe osteoarthritis." (PMID 38789630, 2024). "Chrysophanol has an anti-inflammatory effect on osteoarthritis in mice in vitro by regulating the SIRT6/NF-kappa B and Nrf2/NF-kappa B signaling pathways." (PMID 38746013, 2024). "Several studies have showed the therapeutic effect of SIRT6 overexpression such as protecting cardiomyocytes from apoptosis/necrosis and ameliorating osteoarthritis through inhibiting extracellular matrix degeneration and cellular senescence." (PMID 37199639, 2023). "Here we show that Sirt6 deficiency exaggerates chondrocyte senescence and osteoarthritis progression, whereas intra-articular injection of adenovirus-Sirt6 markedly attenuates surgical destabilization of medial meniscus-induced osteoarthritis." (PMID 36496445, 2022). "Expression levels of SIRT6 in peripheral blood mononuclear cells, monocytes, and macrophages are lower in patients with rheumatoid arthritis compared with those with osteoarthritis." (PMID 35463332, 2022). "Clinical analysis has shown that levels of SIRT6 in particular chondrocytes of osteoarthritis patients are significantly reduced." (PMID 35463332, 2022). "Furthermore, similar to AF, deletion of Sirt6 in articular cartilage promotes osteoarthritis, suggesting that cartilaginous tissues are sensitive to Sirt6 loss-of-function." (PMID 40335469, 2025). "Sirt6 inhibition could promote the release of proinflammatory cytokines by macrophages in the synovial membrane, induce M1 polarization in macrophages and inhibit M2 polarization in vitro, and Sirt6 overexpression alleviated osteoarthritis in vivo." (PMID 35443857, 2022). "New studies have found that Sirt6 Tg mice are resistant to the release of inflammatory factors and the progression of osteocyte death, bone resorption, and osteoarthritis after ischemic surgery, while osteoblast/osteocyte-specific SIRT6 knockout mice show severe bone loss and deformity." (PMID 36275897, 2022). "In vivo, specific ablation of Sirt6 in chondrocytes exacerbated osteoarthritis." (PMID 36496445, 2022). "Targeting Sirt6 represents a promising new approach for osteoarthritis." (PMID 36496445, 2022). "Based on these important findings, K33 or other lysine sites in Sirt6 may be deacetylated by Sirt1 in chondrocytes in the context of chondrocytes senescence and osteoarthritis." (PMID 36496445, 2022). "Overexpression or activation of Sirt6 can prevent the progression of osteoarthritis." (PMID 26639398, 2015). "Developing specific activators of Sirt6 may be beneficial for the prevention or therapeutic treatment of osteoarthritis." (PMID 26639398, 2015). "Therefore, preferential activation of Sirt6 in chondrocytes could represent a novel and effective strategy to prevent and treat osteoarthritis." (PMID 39335461, 2024).
osteoarthritis (continued). "SIRT6 levels in the articular chondrocytes of osteoarthritis patients are significantly reduced; therefore, overexpression of SIRT6 could reduce the senescence of chondrocytes and prevent the development of osteoarthritis." (PMID 35463332, 2022). "Developing specific Sirt6 inducers may help prevent or treat osteoarthritis." (PMID 35443857, 2022). "Therefore, we hypothesized the protective role of Sirt6 against osteoarthritis was achieved through suppressing NF-κB signaling." (PMID 26639398, 2015). "In line with this, activation of SIRT6 with MDL‐800198 (compound 7a in the “SIRT Activators” section) was shown to prevent chondrocyte senescence and osteoarthritis development." (PMID 39215785, 2025). "Sirtuin 6 (Sirt6), a member of the sirtuin family of NAD+-dependent enzymes, also appears to play a central role in the pathogenesis of osteoarthritis by reducing the inflammatory response and chondrocyte senescence." (PMID 39335461, 2024). "However, it remains unknown whether Sirt6 participates in the development of osteoarthritis." (PMID 26639398, 2015). "It was reported that macrophages have an important function in synovial inflammation, and our team revealed that the amounts of Sirt6, a nicotinamide adenine dinucleotide (NAD)+-dependent histone deacetylase, decrease during synovial inflammation and osteoarthritis." (PMID 35443857, 2022). "Through the modulation of the SIRT6/NF-KB and Nrf2/NF-KB signaling pathways to activate SIRT6 and downregulate the expression of ADAMTS-4, MMP-13, COX-2, and iNOS, articular chondrocyte degradation is prevented, and the inflammatory response in osteoarthritis (OA) is mitigated." (PMID 39857301, 2025). "However, to our knowledge, there is still no study identifying the roles of Sirt6 in cartilage or/and osteoarthritis." (PMID 26639398, 2015).
gastric cancer (19 papers, 2017 to 2025). A primary or metastatic malignant neoplasm involving the stomach. "Sirt6 expression levels varied among gastric cancer cells, and high expression levels were associated with higher overall survival rates." (PMID 38254877, 2024). "In addition, higher expression of SIRT6 was associated with shorter survival of gastric cancer patients and non-small cell lung cancer patients." (PMID 30524965, 2018). "Besides, high SIRT6 expression was associated with poor OS of gastric cancer." (PMID 35172823, 2022). "Ad-Sirt6-induced Sirt6 overexpression downregulated Sirt1 in gastric cancer cells, whereas shSirt6-mediated Sirt6 silencing upregulated Sirt1 expression." (PMID 38254877, 2024). "By modulating the activity of HIF-1α and c-Myc, STAT3 significantly enhances AEG and proliferation in gastric cancer cells, underscoring its pivotal role in the SIRT6-regulated AEG pathway." (PMID 39906672, 2024). "Sirt6 expression levels were lower in SNU-638 cells (gastric cancer cell line) than in the control cells (HPSECs)." (PMID 38254877, 2024). "Sirt6 overexpression induced by Ad-Sirt6 increased ROS accumulation, whereas Sirt6 knockdown via shSirt6 decreased ROS production in gastric cancer cells." (PMID 38254877, 2024). "In this study, we examined the anti-tumorigenic effect of Sirt6 on inducing ROS-related gastric cancer cell death by suppressing Sirt1 expression." (PMID 38254877, 2024). "Although the anti-cancer effects of Sirt6, especially concerning the inhibition of Sirt1, have been documented for various cancers, this phenomenon remains unexplored in the context of gastric cancer." (PMID 38254877, 2024). "Among the seven mammalian sirtuin proteins, Sirt6 and Sirt1 seem to be key factors of gastric cancer cell death." (PMID 38254877, 2024). "MDM2-modulated Sirt6 upregulation and Sirt1 downregulation promoted gastric cancer cell death via increasing ROS accumulation." (PMID 38254877, 2024). "Sirt6- and Sirt1-mediated gastric cancer cell death via ROS regulation was demonstrated previously in many types of cancer but not in gastric cancer." (PMID 38254877, 2024). "Studies have shown that SIRT6 inhibits the growth of gastric cancer by suppressing the JAK2/signal transducer and activator of the transcription-3 pathway." (PMID 38548549, 2024). "This study is the first to examine the role of Sirt1 and Sirt6 in the regulation of gastric cancer cell death." (PMID 38254877, 2024). "In a SNU-638 xenograft mouse model, Sirt6 overexpression significantly decreased gastric cancer tumor volume, suggesting that Sirt6 exerts anti-tumorigenic effects." (PMID 38254877, 2024). "In gastric cancer tissues and cell lines, a low expression of SIRT6 leads to the upregulation of HIF-1α and the activation of various AEG enzymes, thereby promoting gastric cancer cell growth." (PMID 39906672, 2024). "Univariate Cox regression analysis revealed that HDAC1, HDAC5, HDAC8, SIRT3, and SIRT6 were significant predictors of gastric cancer." (PMID 37649598, 2023). "Our results indicated probably staged roles of SIRTs, particularly SIRT6, in the intestinal-type gastric cancer inflammation-carcinoma sequence." (PMID 36324577, 2022). "SIRT6 overexpression also induced apoptosis of gastric cancer cells via regulating JAK2/STAT3 signaling." (PMID 34927546, 2021). "The results suggested that SIRT4, SIRT6, and SIRT7 were associated with Lauren classification and SIRT3-5 were associated with pStage in gastric cancer." (PMID 29088792, 2017). "To examine whether SIRT6 levels are related to the extent of cachexia, we measured SIRT6 levels in a cohort of patients with gastric cancer (TNM staging III)." (PMID 39971710, 2025).